DCD (dermcidin)
Diseases named in the same sentence as DCD in open-access papers (continued):
Sharing a sentence is not in itself a finding about the gene and the disease.
prostate carcinoma (4 papers, 2008 to 2025). A carcinoma that arises from epithelial cells of the prostate gland. "Prostate cancer patients are associated with lower level of NO and higher level of both proteins dermcidin (OR = 1.12, P<0.001) and hs-TroponinT (OR = 1.76, P<0.001)." (PMID 31300527, 2019). "Binary logistic regression analysis of the dermcidin against the prostate cancer status (reference group: healthy participants) shows that there is a positive association with dermcidin and the prostate cancer status." (PMID 31300527, 2019). "In the present study, we observed that the dermcidin concentration was higher in prostate cancer patients with the simultaneous low production of NO, while in healthy participants’ nitric oxide production was found to be normal." (PMID 31300527, 2019). "It was found from the ELISA experiment that the average dermcidin level in prostate cancer patients was 71.5 (59.8–82.4) nM." (PMID 31300527, 2019). "Specifically, DCD expression by primary tumours from patients with gastro-oesophageal, pancreatic, bile duct, and prostate cancer was analysed." (PMID 18594538, 2008). "Therefore, on average, dermcidin level is higher in prostate cancer patients as compared with the healthy participants of the study." (PMID 31300527, 2019). "However, Wang and coworkers identified DCD/HCAP mRNA in primary prostate cancers and bone metastasis specimens, results that differ from those presented here." (PMID 18594538, 2008). "Moreover, if DCD was present in the immortalised prostate cancer cell lines used, it was present at a very low level." (PMID 18594538, 2008). "DCD mRNA expression was undetectable in the primary prostate cancer samples." (PMID 18594538, 2008). "Other sources suggest that DCD may well be expressed in prostate cancer." (PMID 18594538, 2008). "Our objective was to evaluate if there is any correlation between IR (through the mediation of dermcidin protein, NO, HOMA score, Insulin, HDL) and status of prostate cancer outcome which is evaluated as health status." (PMID 31300527, 2019). "In contrast with a weak positive correlation with the healthy control group, we observed a moderate negative correlation between NO and dermcidin levels in prostate cancer patients." (PMID 31300527, 2019). "The results from primary prostate tissue suggest that DCD was not expressed by primary prostate cancer." (PMID 18594538, 2008). "There was moderate expression of DCD in one of the pancreatic cell lines but low/absent expression in all prostatic cancer cell lines, findings that correlated with the overall DCD expression patterns by the respective primary cancer tissues." (PMID 18594538, 2008). "Prostate cancer cell lines demonstrated low or absent levels of DCD expression." (PMID 18594538, 2008). "A further hypothesis on the lack of DCD mRNA expression in the prostate cancer samples analysed in the present study is selective degradation of DCD mRNA." (PMID 18594538, 2008).
acute myocardial infarction (3 papers, 2012 to 2025). Necrosis of the myocardium, as a result of interruption of the blood supply to the area. "In 2011, we have reported, for the first time ever, the association of dermcidin with acute myocardial infarction and also reported that the systemic increase of nitric oxide decreased the plasma dermcidin level for a better prognostic outcome of the condition." (PMID 24649391, 2014). "Another study showed elevated dermcidin levels in patients with acute coronary syndrome and acute myocardial infarction (they were significantly higher in the latter condition)." (PMID 40943120, 2025). "The authors mention insulin as a potential molecule that can reverse this effect and also suggest considering higher doses of aspirin during myocardial infarction to overcome this dermcidin effect." (PMID 40943120, 2025).
breast tumors (3 papers, 2021 to 2025). "DCD, a secreted antimicrobial peptide, has been found to be dysregulated in a subset of breast tumors." (PMID 41200166, 2025). "Another partner of interaction with sGRP78 is such a protein as dermcidin (DCD), a cell-secreted growth and survival factor, whose gene was amplified and overexpressed in a subset of breast tumors." (PMID 34943954, 2021).
Cachexia (3 papers, 2003 to 2020). Severe weight loss, wasting of muscle, loss of appetite, and general debility related to a chronic disease. "As glycosylation appears essential to the ability of PIF to induce cachexia, we attempted to correlate the ability of dermcidin expression to promote survival with structural mutations designed to alter N-glycosylation." (PMID 16685272, 2006).
coronary artery disease (3 papers, 2012 to 2025). "It should be mentioned that the injection of dermcidin was capable of developing coronary artery disease in the animal model in the suboptimal amount of ADP within 30 min." (PMID 22448321, 2012). "And, as such, the use of chronic aspirin in T1BDM might be helpful to prevent coronary artery disease through the inhibition of dermcidin synthesis as well as through increased systemic insulin synthesis due to the stimulation of nitric oxide synthase." (PMID 24649391, 2014). "The dermcidin-induced platelet aggregation was compared to that induced by ADP, which is reported to be the most important platelet aggregating agent in the genesis of the coronary artery disease in man due to the aggregation of platelets in the coronary artery." (PMID 22448321, 2012).
gastric cancer (3 papers, 2021 to 2024). A primary or metastatic malignant neoplasm involving the stomach. "In our analysis of human-derived proteins in tongue coating, we observed a significant downregulation of KRT2, KRT9, and DCD in the tongue coating of gastric cancer patients." (PMID 38191439, 2024). "Downregulation of KRT2, KRT9, and DCD collectively indicates a decreased microbial resistance in the oral cavity of gastric cancer patients." (PMID 38191439, 2024). "Dermcidin expression in gastric cancer reflects overall survival and is positively correlated with lymph node metastasis." (PMID 34198581, 2021). "A total of 5 proteins, including KRT2, KRT9, DCD, EWSR1, and CACNA1G, were downregulated in gastric cancer patients in both cohorts." (PMID 38191439, 2024).
Insulin resistance (3 papers, 2014 to 2024). Increased resistance towards insulin, that is, diminished effectiveness of insulin in reducing blood glucose levels. "Vaspin and visfatin are closely linked to metabolic disorders, while dermcidin and chemerin have antimicrobial properties, but they are also related to insulin resistance and inflammation." (PMID 39795898, 2024). "Therefore, the confirmed low levels of Transthyretin and Dermcidin in athletes suggest a role of these proteins in adaptative response to sports and two potential new targets for treating insulin resistance." (PMID 35360242, 2022). "Moreover, it was found that chemerin, visfatin, vaspin, irisin and dermcidin are correlated positively, while obestatin and adropin negatively, with BMI (body mass index) and HOMA-IR (homeostatic model assessment for insulin resistance)." (PMID 39795898, 2024).
Alzheimer disease (2 papers, 2021 to 2023). A progressive, neurodegenerative disease characterized by loss of function and death of nerve cells in several areas of the brain leading to loss of cognitive function such as memory and language. "A combination of four tear proteins—lipocalin 1, dermcidin, lysozyme C, and lacritin—was shown to have 81% sensitivity and 77% specificity for Alzheimer’s disease." (PMID 36983883, 2023). "Furthermore, the tear fluid of Alzheimer’s disease patients included considerably lower amounts of lysozyme, lipocalin 1, and lacritin, as well as higher levels of dermcidin." (PMID 36983883, 2023).
asthma (2 papers, 2021 to 2023). "For example, an abundance of dermcidin was identified in exhaled breath condensate in asthma patients." (PMID 34198581, 2021).
atherosclerosis (2 papers, 2012 to 2014). A disease characterized by the build-up of fatty material and calcium deposition in the arterial wall resulting in partial or complete occlusion of the arterial lumen. "In this context, an environmentally induced stress protein identified to be dermcidin isoform 2 (dermcidin) has been reported which was found to be both a diabetogenic and a hypertensive agent posing an important threat for the development of atherosclerosis." (PMID 24649391, 2014). "The association of dermcidin in the environmentally induced type 1B diabetes mellitus (T1BDM) and in atherosclerosis has also been reported recently." (PMID 24649391, 2014). "The stimulated synthesis of dermcidin due to the lack of systemic insulin might play an important role in the development of atherosclerosis in T1BDM." (PMID 24649391, 2014).
atopic dermatitis (2 papers, 2022 to 2025). "AMPs including defensins, cathelicidin, psoriasin, dermcidin, and ribonucleases, play a crucial role in skin immunity but may be dysregulated in atopic dermatitis." (PMID 40771803, 2025).
Sepsis (2 papers, 2025). Sepsis is defined as life-threatening organ dysfunction caused by a dysregulated host response to infection. "To understand the mechanisms underlying pro-DCD-mediated protection, we evaluated the effects of PEGylated pro-DCD-C34S (PEG-proDCD-C34S) on sepsis-induced inflammatory injury and bacterial dissemination." (PMID 40806779, 2025). "After extensive extraction with Triton X-114 to remove endotoxin contaminants, we evaluated the therapeutic efficacy of highly purified pro-DCD, pro-DCD-C34S, and pegylated pro-DCD-C34S in a murine model of experimental sepsis." (PMID 40534887, 2025). "To explore the functional role of pro-DCD in sepsis, we examined the impact of antigen affinity-purified anti-pro-DCD IgGs on sepsis-induced systemic inflammation and tissue injury." (PMID 40806779, 2025). "To further elucidate pro-DCD’s protective mechanism, we examined its impact on bacterial clearance in a murine sepsis model." (PMID 40806779, 2025). "On the other hand, recombinant pro-DCD conferred a significant protection against lethal sepsis when administered repeatedly at 2 h or 24 h post-onset." (PMID 40534887, 2025). "While antigen-affinity-purified pro-DCD pAbs exacerbated sepsis-induced systemic inflammation and tissue injury, recombinant pro-DCD-C34S and its PEGylation derivatives conferred significant protection when administered at 24 h post-CLP." (PMID 40806779, 2025). "In this review, we summarize recent evidence supporting pro-DCD as a regulator of innate immunity in sepsis." (PMID 40806779, 2025). "To understand the extracellular role of pro-DCD in sepsis, we synthetized thirteen peptides corresponding to different regions of human pro-DCD and used them to profile the epitopes of rabbit polyclonal antibodies that we raised against human pro-DCD." (PMID 40534887, 2025). "Consistently, these anti-pro-DCD antibodies exacerbated sepsis-induced liver injury and appeared to dose-dependently increase sepsis-induced animal lethality." (PMID 40534887, 2025). "Collectively, these findings indicate that both pro-DCD and pro-DCD-C34S derivatives confer significant protection against lethal sepsis, with PEGylation further enhancing the therapeutic potential of pro-DCD-C34S." (PMID 40806779, 2025). "While DCD has established antimicrobial activity, emerging evidence suggests that pro-DCD plays a broader immunoregulatory role during sepsis." (PMID 40806779, 2025). "Furthermore, these anti-pro-DCD antibodies worsened sepsis-induced liver injury and dose-dependently increased sepsis-induced animal lethality, suggesting a potentially protective role for pro-DCD in experimental sepsis." (PMID 40806779, 2025). "To investigate the extracellular role of pro-DCD in sepsis, we generated some polyclonal antibodies (pAbs) against human pro-DCD and characterized their epitope profile by dot blotting using 13 synthetized peptides (“P1–P13”) spanning different regions of the protein." (PMID 40806779, 2025). "Here, we review recent evidence supporting pro-DCD as a regulator of innate immunity in sepsis." (PMID 40806779, 2025). "However, future independent studies are needed to investigate whether pro-DCD loses its protective effects against lethal sepsis when LC3 is pharmacologically inhibited or genetically disrupted in experimental animals." (PMID 40534887, 2025). "However, future independent studies are needed to determine whether pro-DCD’s protective effects against sepsis are lost upon pharmacological inhibition or genetic disruption of LC3 in experimental settings." (PMID 40806779, 2025).
skin infection (2 papers, 2014 to 2018). An inflammatory process affecting the skin, caused by bacteria, viruses, parasites, or fungi. "We will discuss the peptides (defensins, cathelicidins, RNase7, dermcidin) and other mediators (toll-like receptor, IL-1 and IL-17) that comprise the host defense against S. aureus skin infection, as well as the various mechanisms by which S. aureus evades host defenses." (PMID 24840573, 2014).
cholangiocarcinoma (1 paper, 2008). A carcinoma that arises from the intrahepatic biliary tree (intrahepatic cholangiocarcinoma) or from the junction, or adjacent to the junction, of the right and left hepatic ducts (hilar cholangiocarcinoma). "Five samples (45.5%) expressed DCD mRNA, three of which had CT values 25.5–30.5 defined as high levels of expression: 2 metastatic pancreatic adenocarcinomas and one poorly differentiated cholangiocarcinoma." (PMID 18594538, 2008).
chronic periodontitis (1 paper, 2013). A chronic inflammatory process that affects the tissues that surround and support the teeth. "Moreover, dermcidin was identified only in chronic periodontitis subjects." (PMID 24098404, 2013).
COVID-19 (1 paper, 2023). A disease caused by infection with severe acute respiratory syndrome coronavirus 2. "The study found that autoantigens like NXPH-1, PCSK-1, SLC2A10, and DCD correlated with markers of COVID-19 severity like D-dimers, ferritin, C-reactive protein, and lactate which can increase in severe COVID-19." (PMID 36937488, 2023).
cutaneous melanoma (1 paper, 2021). A primary melanoma arising from atypical melanocytes in the skin. "RT-PCR analysis showed that the precursor (Dermcidin, DCD) is highly expressed in human skin, melanocytic nevus tissue, and cutaneous melanoma tissue." (PMID 34680498, 2021).
E. coli infection (1 paper, 2025). "Furthermore, the migrasomes produced by BM-MSCs are enriched with high concentrations of the antimicrobial peptide dermcidin (DCD), which significantly reduces lung bacterial load and enhances macrophage LAP following E. coli infection." (PMID 40443653, 2025).
eczema (1 paper, 2023). "Notably, AMPs such as PI3 or LCE3A are also downregulated, while DCD, an antimicrobial component of sweat typically downregulated in eczema, shows the opposite direction." (PMID 37298605, 2023). "Dermcidin, an AMP often suppressed in eczema, also shows a similar pattern." (PMID 37298605, 2023).
endothelial dysfunction (1 paper, 2019). In vascular diseases, endothelial dysfunction is a systemic pathological state of the endothelium (the inner lining of blood vessels) and can be broadly defined as an imbalance between vasodilating and vasoconstricting substances produced by (or acting on) the endothelium. "Previously, it was found that dermcidin impaired the insulin activity through NO inhibition and the found result of elevated HbA1c level and lower level of NO are the indication of endothelial dysfunction which actually precipitates cardiovascular disease." (PMID 31300527, 2019).
extramammary Paget disease (1 paper, 2021). A malignant neoplasm in which there is infiltration of the skin by neoplastic large cells with abundant pale cytoplasm and large nuclei with prominent nucleoli (Paget cells). "It is therefore urgently needed to further investigate the actual impact of dermcidin on the molecular mechanism of the development of extramammary Paget’s disease." (PMID 34198581, 2021). "To clarify the characteristics of positive dermcidin in extramammary Paget’s disease, we investigated the clinical characteristics of positive dermcidin extramammary Paget’s disease patients." (PMID 34198581, 2021). "In conclusion, dermcidin has the potential to help toward the prognosis of extramammary Paget’s disease at the moment of surgical resection of the tumor." (PMID 34198581, 2021). "To clarify this issue, we investigated the differences in age, sex, depigmentation as the manifestation of extramammary Paget’s disease, and lymph node metastasis between dermcidin high- and low-expressing groups." (PMID 34198581, 2021). "To investigate the potential of dermcidin in extramammary Paget’s disease, we investigated dermcidin expression in tumors using the immunostaining technique." (PMID 34198581, 2021). "In this study, we investigated the potential of dermcidin as a biomarker for the prognosis of extramammary Paget’s disease." (PMID 34198581, 2021). "The reason that positive dermcidin expression was observed in clinical patients with unfavorable outcomes who suffered from extramammary Paget’s disease remains unclear." (PMID 34198581, 2021). "Univariate analysis identified that positive dermcidin showed a significantly increased hazard ratio in overall survival, suggesting that dermcidin might be a prognostic factor for extramammary Paget’s disease." (PMID 34198581, 2021). "Although the impact of dermcidin on prognosis might be limited, dermcidin might become a tool for estimating prognosis in patients with extramammary Paget’s disease in some cases." (PMID 34198581, 2021). "One possible limitation of our study was that the number of patients involved might not be sufficient to investigate the more detailed characteristics of dermcidin-positive patients with extramammary Paget’s disease." (PMID 34198581, 2021). "Our results suggest that dermcidin might be an independent prognostic factor in patients with extramammary Paget’s disease." (PMID 34198581, 2021). "Because HER-2 signaling is also involved in the pathogenesis of extramammary Paget’s disease, it is assumed that dermcidin might also activate HER-2 signaling in extramammary Paget’s disease and subsequently lead to the development of tumor growth." (PMID 34198581, 2021). "We next investigated the prognostic impact of dermcidin in extramammary Paget’s disease." (PMID 34198581, 2021). "A previous study showed a negative dermcidin expression in patients with extramammary Paget’s disease." (PMID 34198581, 2021). "Although there were cases with no staining of dermcidin, these antibodies showed that several patients diagnosed with extramammary Paget’s disease had different expression patterns of dermcidin in the tumor, such as minuscule, average, and strong expression." (PMID 34198581, 2021). "We identified that there are two groups, dermcidin-positive and -negative extramammary Paget’s disease." (PMID 34198581, 2021). "Although previous studies have reported that extramammary Paget’s disease has no positive staining against dermcidin, 14 out of 60 patients showed positive staining of dermcidin in our study." (PMID 34198581, 2021). "These unexpected results prompted us to investigate the characteristics of extramammary Paget’s disease with or without dermcidin-positive reaction in further detail." (PMID 34198581, 2021).
extramammary Paget disease (continued). "Although extramammary Paget’s disease is usually characterized by no expression of dermcidin we speculated that there were differences in clinical characteristics in extramammary Paget’s disease between positive and negative expression of dermcidin." (PMID 34198581, 2021). "Because extramammary Paget’s disease is believed to be a malignant tumor derived from the apocrine glands, representing a negative expression of dermcidin in normal tissue, the possible role of dermcidin as a biomarker in patients with extramammary Paget’s disease has not been investigated." (PMID 34198581, 2021).